MEN1 (menin 1)
Diseases named in the same sentence as MEN1 in open-access papers (continued):
Sharing a sentence is not in itself a finding about the gene and the disease.
leukemia (continued). "The role of menin in other cancers apart from CRC, prostate, MLL-fusion leukemias, and MEN1 syndrome spectrum tumors is largely unknown and certainly merits further investigation." (PMID 31763368, 2019). "However, we did note that a substantial number of Men1f/f + Cre mice succumbed to leukemia that had failed to rearrange both alleles, implying strong selective pressure against loss of Men1." (PMID 33542482, 2021). "For example, MLL rearrangement is a common event in pediatric leukemias, and MLL-rearranged leukemias exquisitely depend on MLL1/MEN1 for survival." (PMID 37460547, 2023). "Combined Menin inhibitor and potent Ikaros degrader treatment strongly increased toxicity in leukemia cells and allowed for curative treatment of PDX, including a PDX model which had been demonstrated to succumb from MEN1‐mutant resistant leukemia after a relatively short latency." (PMID 39887730, 2026). "Most MEN1 binders were highly selective towards MLLr cell lines in comparison to MLLr-negative leukemias." (PMID 38003662, 2023). "Furthermore, Men1−/− MN1-driven AML cells failed to propagate leukemia in most recipients (13/15), with a failure to rearrange both alleles in one of the animals." (PMID 33542482, 2021).
adrenal tumors (21 papers, 2012 to 2026). "For example, in a prospective series of 38 patients with proven germline MEN1 mutation, two had functional adrenal tumors resulting in CS and/or virilization: one had bilateral adenomas and one had ACC." (PMID 37409236, 2023). "The causal link between MEN1 and adrenal tumors is supported by the development of adrenal tumors or hyperplasia in mice carrying deletions of specific exons of the MEN1 gene." (PMID 34680514, 2021). "Evaluation for MEN1-associated adrenal tumors is primarily based on imaging either with CT or MRI that can be performed in conjunction with pancreatic imaging, with biochemical testing indicated only in the setting of symptoms or signs of a functional tumor or the presence of a tumor >1 cm." (PMID 31263451, 2019). "We obtained genomic DNA from some of these adrenal tumours, and by comparison with normal tissue (from the liver of the same animal), observed that these adrenal tumours had undergone loss of heterozygosity at the Men1 locus, with relative over-representation of the deleted allele." (PMID 22708734, 2012). "In a retrospective analysis of MEN1 patients that included 19 patients with CS, three of 14 subjects with an identifiable cause for their CS (21%) had ACTH-independent CS due to adrenal tumors, two of these three from ACC." (PMID 37409236, 2023). "Even if also malignant adrenal tumors may occur in MEN1, adrenal involvement in MEN1 seems to be less relevant than pancreaticoduodenal manifestation." (PMID 37444604, 2023). "Adrenal tumours are a common feature of MEN1 that can affect more than half of the patients." (PMID 31482957, 2019). "Patients with MEN1 and adrenal tumors should receive annual imaging, with consideration for surgical tumor resection if tumors are larger than 4 centimeters, display atypical radiological features and are 1–4 cm in size, or show significant growth over 6 months." (PMID 31263451, 2019). "MEN1 associated adrenal tumors are mostly small, benign, and nonfunctioning." (PMID 37444604, 2023).
adrenal adenoma (20 papers, 2014 to 2026). "In general ACC is greater than 10-fold more common among MEN1 adrenal lesions than among sporadic adrenal incidentalomas." (PMID 37409236, 2023). "That being the case, benign adrenal adenomas are still much more common among MEN1 patients with functional adrenal masses resulting in ACTH-independent CS." (PMID 37409236, 2023). "Participant E had an established clinical diagnosis of MEN1, with three major manifestations as well as an adrenal gland adenoma." (PMID 34711244, 2021). "However, in our case, adrenal cortical adenoma and pheochromocytoma separately coexisted in the same adrenal gland, which is extremely rare, and even more so in the setting of the MEN1." (PMID 27572829, 2016). "We report a comprehensive genetic characterization of three adrenal cortical tumor samples obtained from a familial MEN1 patient, operated for the rapid progression of an initially stable nonfunctional adrenal incidentaloma." (PMID 41806143, 2026). "Adrenocortical adenoma/hyperplasia never resulted to be the first MEN1 manifestation in our series of patients." (PMID 30428914, 2018). "Almost 50% of MEN1 patients could develop adrenal adenomas or hyperplasia, which are mainly nonfunctioning and benign." (PMID 26161274, 2015). "Most of these adrenal cortical adenomas have been considered non-functional, but recent studies have suggested that APA could be a more common component of the MEN1 adrenal phenotype than previously considered." (PMID 24343173, 2015).
meningioma (19 papers, 2012 to 2025). A generally slow growing tumor attached to the dura mater. "In summary, meningiomas have been proposed as a component of MEN1 yet data are few to strongly support the role of loss of MEN1 function in meningioma pathogenesis." (PMID 36325452, 2022). "On the contrary, adrenal and skin lesions, as well as meningiomas, are less specific for MEN1 and MEN4." (PMID 37761922, 2023). "Meningioma was found late in the clinical course with a mean time of 17.6 years after the onset of MEN1." (PMID 36325452, 2022). "CNS tumors include asymptomatic meningiomas in 8% of MEN1 patients, while ependymomas and schwannomas affect about 1% of cases." (PMID 33312161, 2020). "Several other neoplasms occur with increased frequency in MEN1 including foregut carcinoid tumors, adrenocortical tumors, cutaneous tumors, meningiomas and ependymomas, tumors of smooth muscle, and very rarely pheochromocytomas." (PMID 31263451, 2019). "This may necessitate advanced molecular techniques, such as methylation profiling, to distinguish them from other tumors more commonly seen in MEN1, such as meningioma." (PMID 41155355, 2025). "Although meningiomas are not commonly associated with MEN1 syndrome, there have been reports of meningiomas in families with MEN1." (PMID 41155355, 2025). "Numerous more recent studies report that MEN1 patients also develop smooth muscle tumors (leiomyomas, leiomyosarcomas), CNS tumors (meningiomas, schwannomas, ependymomas), skin tumors (angiofibromas > collagenomas > lipomas > melanoma), as well as breast, urological, and other tumors." (PMID 41463062, 2025). "Familial MEN1 (n = 129): Meningiomas were present in four (3.1%) patients." (PMID 37484956, 2023). "Herein, meningioma was present in 5/185 (2.7%) cases: three familial MEN1 mutation-positive, one familial, and one sporadic MEN1 mutation-negative patients." (PMID 37484956, 2023). "Meningiomas occur with greater frequency in patients with germline mutations of genes such as type-2 neurofibromatosis (NF2), type-1 neurofibromatosis (NF1, 19–24% of adolescent meningiomas), type-1 multiple endocrine neoplasia (MEN1), SMARCB1, LZTR1, or SMARCE1 genes." (PMID 37760490, 2023). "Sporadic MEN1 (n = 55): Meningioma was present in one (1.8%) patient." (PMID 37484956, 2023). "Meningiomas can also be genetically determined and are present in several genetic syndromes such as: neurofibromatosis type 2 (NF2), which is most frequently associated with meningiomas, Gorlin, Li Fraumeni, Cowden, von Hippel–Lindau, and multiple endocrine neoplasia type 1 (MEN1)." (PMID 34679551, 2021). "Tumors associated with MEN1 include meningiomas and ependymomas but not glioma." (PMID 23137305, 2012). "In 2004, in a study of 74 eligible MEN1 patients prospectively evaluated at the National Institutes of Health (NIH), there were six cases (8.1%) of meningioma diagnosed at a mean age of 50.8 years (range 29-76)." (PMID 36325452, 2022). "Screening for meningioma is not recommended in MEN1 patients, but if one is identified, it should be managed similarly to patients without MEN1." (PMID 36325452, 2022). "Meningiomas arising in MEN1 setting are usually silent, thus the diagnosis is often late, with a mean interval of 18 years from the diagnosis of MEN1; they have a higher incidence in patients with ZES in the MEN1 setting than in patients with sporadic ZES." (PMID 24961548, 2014). "Thus far there has been no strong evidence supporting a role of MEN1 in the pathogenesis of meningiomas." (PMID 36325452, 2022). "No other series of MEN1 patients and meningioma has yet been published to confirm the NIH findings, although patients with meningiomas have been reported in other publications, including one patient who died of a meningioma." (PMID 36325452, 2022).
pheochromocytoma (19 papers, 2015 to 2026). "Two patients with NET had mutations in MEN1 gene, one patient with pheochromocytoma had a pathogenic VHL mutation in exon 3, and one patient with paraganglioma had a variant of uncertain significance in SDHB c.287-3C>G." (PMID 29262620, 2017). "We identified two patients (patients 22 and 23) with a germline MEN1 mutation and pheochromocytoma, whereas all the other tested genes were normal." (PMID 25494863, 2015). "Together with the single case reports available in the literature, this large cohort supports the hypothesis that in some families SDH mutations may have a role in PA formation and MEN1 mutations may have a role in the development of pheochromocytoma." (PMID 25494863, 2015). "Six patients had a confirmed MEN1 mutation and pheo/PGL (23, –, 25): five patients with pheochromocytoma and one head and neck PGL." (PMID 25494863, 2015). "Unlike the situation with MEN1 and the phaeochromocytoma pre-disposing gene mutations there is generally a clear genotype-phenotype correlation between gene mutation and clinical phenotype in MTC." (PMID 28965289, 2017). "However, MEN1 with concomitant pheochromocytoma is extremely rare." (PMID 27572829, 2016). "Mutations in some genes have been found only in single patients or families (e.g., MEN1, EGLN1, EGLN2, MDH2, IDH1, BAP1, BRAF); therefore, their role in the formation of paragangliomas/pheochromocytomas cannot be reliably confirmed." (PMID 28187001, 2017). "LOH at the SDHB locus in the PA samples and LOH at the MEN1 locus in the pheochromocytoma samples was demonstrated, suggesting, although not proving, the pathogenic role of these genes in these nonclassically disease-specific tissues." (PMID 25494863, 2015). "Both pheochromocytomas showed LOH in the MEN1 gene, supporting, although not proving, the pathogenic role of MEN1 in these tumors." (PMID 25494863, 2015).
von Hippel-Lindau disease (18 papers, 2014 to 2025). An autosomal dominant disorder caused by pathogenic variants in the VHL gene, leading to an increased risk of various benign and malignant tumors, including hemangioblastomas, retinal hemangiomas, endolymphatic sac tumors, renal cell carcinoma, and pheochromocytomas. "Somatostatinoma may be sporadic (93.1%) or associated with neurofibromatosis type 1 (NF1), MEN1, and Von Hippel–Lindau syndromes (6.9%)." (PMID 33204258, 2020). "These lesions are most commonly sporadic but can also be a part of genetic syndromes such as Multiple Endocrine Neoplasia 1 (MEN1), Von Hippel-Lindau disease VHL, Neurofibromatosis1 (NF-1), and Tuberous Sclerosis (TSC)." (PMID 38672582, 2024). "The familiar syndromes include the multiple endocrine neoplasia type 1 (MEN1), von Hippel–Lindau disease (VHL), neurofibromatosis type 1 (NF1) and tuberous sclerosis complex (TSC)." (PMID 36830839, 2023). "Approximately 10% of p-NETs are due to an inherited syndrome, which includes multiple endocrine neoplasia type 1 (MEN1), von Hippel-Lindau disease (VHL), neurofibromatosis type 1 (NF1), and tuberous sclerosis complex (TSC)." (PMID 35053593, 2022). "Multiple endocrine neoplasia type 1 (MEN1), von Hippel–Lindau disease (VHL), neurofibromatosis 1 (NF-1) (von Recklinghausen disease), and the tuberous sclerosis complex (TSC) are pancreatic endocrine tumors (PETs)." (PMID 36077529, 2022). "Hereditary syndromes associated with PNETs are Multiple Endocrine Neoplasia type 1 (MEN1), Von Hippel–Lindau disease (VHL), Neurofibromatosis type 1 (NF1), and Tuberous Sclerosis Complex (TSC)." (PMID 34122352, 2021). "While most pNETs are sporadic, some are associated with genetic syndromes such as Multiple Endocrine Neoplasia type 1 (MEN1), Von Hippel-Lindau disease [VHL), neurofibromatosis 1 (NF1), or tuberous sclerosis complex." (PMID 32947997, 2020). "Finally, total pancreaticoduodenectomy could be an option for multifocal p-NETs as they might occur in patients with MEN1 and VHL syndrome." (PMID 35053593, 2022). "Key syndromes include multiple endocrine neoplasia type 1 (MEN1), von Hippel–Lindau disease (VHL), neurofibromatosis type 1 (NF1), and tuberous sclerosis complex (TSC), which are characterized by germline mutations in the tumor-suppressor genes MEN1, VHL, NF1, and TSC1 or TSC2, respectively." (PMID 32850899, 2020). "The majority of GEP-NENs (>95%) occurs in sporadic forms, while 5% of cases are part of a polydistrict syndrome, such as multiple endocrine neoplasm type 1 (MEN1), neurofibromatosis type 1 (NF1), and von Hippel–Lindau syndrome (VHL)." (PMID 37761243, 2023).
parathyroid hyperplasia (17 papers, 2000 to 2025). A hyperplasia that involves the parathyroid gland. "In adolescents, mutations in MENIN (MEN1), RET (MEN2), CDKN1B (MEN4), and CDC73 (HPT-JT) predominate, usually leading to multiglandular parathyroid hyperplasia in syndromic forms of PHPT." (PMID 40666157, 2025). "Two of the three patients with parathyroid hyperplasia were screened for MEN1 mutation and were negative." (PMID 31979085, 2020).
parathyroid carcinoma (16 papers, 2008 to 2026). "Patients with familial PHPT or parathyroid cancer had germline mutation in MEN1, CASR, and CDC73, classified as pathogenic or likely pathogenic variants." (PMID 35586626, 2022). "The presence of parathyroid carcinoma in association with MEN1 has been so far described in 16 cases." (PMID 33312161, 2020). "A novel MEN1 mutation, C.1402_1405del GAGG, was found in the parathyroid carcinoma tissue of II-3 and verified by RT-PCR and clone sequencing of MEN1 mRNA in tumor tissue." (PMID 29416715, 2018). "Several germline mutations in CDC73, MEN1, CASR, and PTH are associated with benign sporadic PHPT or parathyroid cancer." (PMID 35586626, 2022). "Genetic variants associated with parathyroid cancer and familial PHPT have been reported, and MEN1, CDC73, and RET mutations are known to be associated with the pathogenesis of parathyroid cancer or familial PHPT." (PMID 35586626, 2022). "There are exceedingly few reports of unequivocal parathyroid carcinomas arising in MEN1 or MEN2A kindred." (PMID 33269427, 2021). "Given the exceedingly low rate of malignant PHPT in MEN1 kindred, other genetic events apart from this aberrancy are expected to drive the invasive behavior in parathyroid carcinoma." (PMID 33269427, 2021). "The syndromic forms of PHPT are due to LOF of tumor suppressor genes, e.g., MEN1, CDKN1B, and CDC73, with patients harboring germline CDC73 mutations having a higher occurrence of parathyroid carcinomas or increased oncogenic signaling (e.g., activating RET mutations)." (PMID 38038882, 2024). "Four out of these five patients had either MEN1 (n=2) or parathyroid cancer (n=2)." (PMID 35586626, 2022). "Summary of clinical features of 16 patients with parathyroid carcinoma and MEN1." (PMID 33312161, 2020). "In addition, Sanger sequencing revealed the LOH of MEN1 IVS9 + 1 G > C in the parathyroid carcinoma tissue of II-3." (PMID 29416715, 2018). "As few as ten patients with MEN1 and MEN2 syndromes (seven and three, respectively) have ever been shown to suffer from malignant parathyroid tumours." (PMID 26658808, 2016). "By contrast, parathyroid carcinomas (PCas) showed a remarkable loss of YAP1 nuclear staining irrespective of the cell division cycle 73 (CDC73) or MEN1 status." (PMID 33670622, 2021).
parathyroid disease (16 papers, 2008 to 2025). "Multiglandular parathyroid disease was present in all MEN1 mutation-positive probands and in 33/34 (97%) relatives." (PMID 29036195, 2017). "An expert panel of physicians, surgeons, and geneticists assembled to provide clinical practice guidelines for MEN1 suggested that gene mutational testing be performed on patients presenting with seemingly sporadic HPT younger than 40 years of age due to multi-gland parathyroid disease." (PMID 33716975, 2021). "Except for parathyroid malignancies, MEN1-related PHPT is the trickiest in all parathyroid diseases." (PMID 37795364, 2023). "Current guidelines advice genetic screening for MEN1 in patients with pHPT if diagnosed at an age below the age of 30 years (or below the age of 40 years in multigland parathyroid disease)." (PMID 30254610, 2018). "The finding of multiple parathyroid disease matches favorably with the diagnosis of MEN1, although it must be noted that most patients with multiglandular hyperplasia do not have familial pHPT." (PMID 23259638, 2012). "The scores of each item in the scoring system were defined as 2 points for recurrent or multigland parathyroid disease, 1 for presence of dpNET, 1 for age at presentation with first MEN1-related primary manifestation ≤ 39, and 1 for presence of angiofibroma or collagenoma." (PMID 39946193, 2025). "Using NGS, we identified three pathogenic variants in two genes (CDC73 and MEN1), 10 likely pathogenic variants in six genes (CASR, CDC73, LRP5, MEN1, SDHA, and VHL), and 39 non-synonymous VUS variants that could be related to parathyroid disease." (PMID 35586626, 2022). "The surveillance program for prototypic tumors of MEN1 in our patient's family did not change in terms of including imaging to prototypic tumors of carriers of CDC73 mutations other than parathyroid disease, as the CDC73 variant detected in some family members is probably benign." (PMID 34889280, 2021). "If we hypothesize MEN1 parathyroid disease to have a spectrum of aggressiveness (defined in terms of number of parathyroid glands involved), then conceptually it is not wrong to treat those with less aggressive disease with a less aggressive parathyroid operation." (PMID 27402205, 2016). "It is very likely, however, that not all MEN1 patients have the same aggressive parathyroid disease." (PMID 27402205, 2016). "However, no single data regarding only the MEN1 PHPT group, or comparing sPHPT with the inherited forms of parathyroid disease, were reported in the study." (PMID 34440663, 2021).